AGO1 (argonaute RISC component 1)
Diseases named in the same sentence as AGO1 in open-access papers (continued):
Sharing a sentence is not in itself a finding about the gene and the disease.
tumor (continued). "The correlations of protein expression of Drosha, AGO1 and AGO2 with sex, age, tumor stage, histological grading and overall survival were evaluated in order to identify their diagnostic and prognostic potential in urothelial cancer." (PMID 29857476, 2018). "circMYC could sponge tumor suppressing miR-20b-5p and let-7e-5p, hence influencing their downstream targets, argonaute RISC component 1 (AGO1) and cryptochrome circadian regulator 2 (CRY2), affecting tumor progression." (PMID 35311066, 2022). "The present data demonstrated that genetic variants in miRNA machinery genes had a significant association with GC susceptibility (DICER and GEMIN4) and malignant behavior such as tumor stage (DICER and GEMIN4) and lymphatic metastasis of GC (GEMIN4 and AGO1) in Chinese Han population." (PMID 29156806, 2017). "As we found many changes in miRNA expression across the five clinical tumor subtypes we had defined above, we asked whether DICER1, DROSHA, DGCR8, AGO1, AGO2, AGO3 or AGO4 expression differs among these subgroups." (PMID 17922911, 2007). "Here we report protein complex of Argonaute 1 (AGO1), Bag of marbles (Bam), and Brain tumor (Brat) proteins and not the individual factor of this complex repression of dMyc mRNA in Drosophila Schneider 2 cells and promote differentiation in cystoblast of Drosophila ovary." (PMID 33907499, 2021). "Furthermore, key regulators of the miRNA pathway, including DROSHA, DGCR8, AGO1 and AGO2 are frequently overexpressed—rather than downregulated—in HCC, and specifically AGO2 overexpression has been shown to promote HCC progression, tumor vascularization and metastasis." (PMID 31732746, 2019).
neurodevelopmental disorder (2 papers, 2024 to 2025). A behavioral and cognitive disorder with onset during the developmental period that involves impaired or aberrant development of intellectual, motor, or social functions. "In the past two years, research has discovered that germline pathogenic variants (GPVs) in DGCR8 are associated with tumor predisposition, and that GPVs in AGO1/2 are linked to neurodevelopmental disorders (NDDs)." (PMID 39457367, 2024).
cardiovascular disease (1 paper, 2015). "Findings related to cardiovascular disease and inflammation (MAP3K7 and SPSB1) could be tied to fenofibrate response, other findings are more difficult to link to the drug's mechanism (e.g., AGO1)." (PMID 26483836, 2015).
hematologic cancers (1 paper, 2025). "Despite these molecular insights, the impact of AGO1 gene deregulation in hematologic cancers is not fully understood." (PMID 41463093, 2025).
hematologic malignancies (1 paper, 2025). "In hematologic malignancies, alterations in AGO1 function could potentially contribute to the dysregulation of hematopoietic gene expression by influencing chromatin architecture and transcriptional reprogramming, thus contributing to leukemic transformation." (PMID 41463093, 2025).
AGO1 also shares sentences with these, for which no sentence is quoted: liver cirrhosis (2 papers); Alzheimer disease (1); bone osteosarcoma (1); cardiac disease (1); cholangiocarcinoma (1); Dengue virus infection (1); DiGeorge syndrome (1); HIV-1 infection (1); inclusion body myositis (1); liver cancer (1); liver disease (1); myeloma (1); oral cancer (1); parasitic infection (1); Pheochromocytoma and Paraganglioma (1); psoriasis (1); rheumatoid arthritis (1); Stroke (1); Wilms’ tumors of the kidney (1).